LMNB1 (lamin B1)
Diseases named in the same sentence as LMNB1 in open-access papers (continued):
Sharing a sentence is not in itself a finding about the gene and the disease.
melanoma (14 papers, 2019 to 2025). A malignant, usually aggressive tumor composed of atypical, neoplastic melanocytes. "In melanoma, early loss of miR-101-3p led to genomic instability, while its reexpression inhibited proliferation and induced apoptosis by targeting Lamin B1, ATRX, CASP3, and PARP." (PMID 40074445, 2025). "For example, knockdown of the known senescence biomarker LMNB1, a gene that encodes the nuclear lamina scaffold protein Lamin B1, induces senescence in human melanoma cells." (PMID 36551868, 2022). "Recent studies have shown that LMNB1 expression could serve as a potential marker of aging in melanoma and could be utilized as a diagnostic reference for hematological malignancies." (PMID 38824174, 2024). "Maybe the loss of LIFR due to LMNB1 knockdown results in reduction of the stemness like properties of melanoma cells leading to senescence." (PMID 35883595, 2022). "Biochemical fractionation revealed that siRNA-mediated reduction of either Lamin A/C or Lamin B1 levels triggered AGO2 nuclear translocation in both A375 melanoma and SHSY5Y neuroblastoma cells." (PMID 38994560, 2024). "Previously published data from our group revealed that LMNB1 influences the heterochromatin state and plays an important role in aging of melanoma cells." (PMID 38431560, 2024). "In order to check the expression of lamin B1 in the MZB-treated melanoma cells, Western blot analysis was performed." (PMID 39683813, 2024). "Conclusively, miR-101-3p directly regulates LMNB1 expression to stabilize nuclear processes in melanoma cells." (PMID 38431560, 2024). "Although siLMNB1 has only a small effect on the cell cycle arrest, in summary, our results demonstrate a significant increase in senescent cells by downregulation of LMNB1 in malignant melanoma cells." (PMID 35883595, 2022). "The role of LMNA is well studied in melanoma, however the role of LMNB1 and the corresponding receptor LBR remained unclear so far." (PMID 35883595, 2022). "Due to the observed strong expression of LMNB1 in melanoma cells, we further aimed to identify its functional relevance." (PMID 35883595, 2022). "p < 0.1) upregulation of LMNB1 in melanoma cell lines and tissues compared to the respective control, NHEMs or nevi." (PMID 35883595, 2022). "Downregulating lamin A and lamin C expression in the B16F10 melanoma line by 90%, but leaving lamin B1 levels intact altered the ratio of type A to type B lamins by approximately 10-fold." (PMID 34069191, 2021). "In a previous study, we showed that LMNB1 is upregulated in several melanoma cell lines." (PMID 38431560, 2024). "Besides, LMNB1 knockdown experiment revealed the implication in important cellular processes driving ER stress leading to cell senescence in malignant melanoma." (PMID 38184636, 2024). "Therefore, the expression of important proteins such as EZH2, ATRX, and LMNB1 can be maintained or adapted to keep and stabilize the increased proliferation rate of melanoma cells." (PMID 38431560, 2024). "Moreover, we have already demonstrated earlier that knockdown of LMNB1 leads to senescence induction and affects chromatin structure in malignant melanoma." (PMID 38431560, 2024). "The increased amount of heterochromatin foci in LBR-knockdown cells indicates that the LBR might have similar functional effects as LMNB1 in melanoma." (PMID 35883595, 2022). "In summary, we could not only show that knockdown of LMNB1 or LBR in melanoma cells leads to senescence but also vice versa, LMNB1 and LBR are significantly downregulated in our senescent models supporting a function in regulation of senescence." (PMID 35883595, 2022). "Conclusively, melanoma cells express high levels of LMNB1 and LBR to prevent senescence." (PMID 35883595, 2022). "The increased amount of heterochromatin foci in LMNB1 knockdown cells could indicate the need for LMNB1 in melanoma cells to prevent cellular ageing or senescence." (PMID 35883595, 2022).
melanoma (continued). "To define the molecular function of LMNB1 in melanoma, we first evaluated its gene expression in the RNA sequencing (RNA-Seq) data of different melanoma cell lines compared to NHEMs (PRJNA839865) and in the primary melanoma compared to melanocytic nevi (GSE112509)." (PMID 35883595, 2022). "To evaluate the effects of lamins on melanoma cell migration and to identify additional mechanisms by which lamins can affect this process, we tested the effects of lamin A and lamin B1 over-expression on melanoma cell migration and on the perinuclear actin organization." (PMID 32987785, 2020). "In this study, we could show that melanoma needs LMNB1 and the LBR for translational processes." (PMID 35883595, 2022). "LMNB1 and the LBR are functionally relevant for melanoma cells to prevent them from cell cycle arrest through influencing the regulation of several genes." (PMID 35883595, 2022). "Changes in the expression of lamins have been linked to various tumour entities; however, the relationship appears to be complex, and less is known about the role of LMNB1 and the LBR in melanoma." (PMID 35883595, 2022). "Our findings suggest that LMNB1 and LBR influence senescence and affect nuclear processes like chromatin condensation and thus are functionally relevant for melanoma progression." (PMID 35883595, 2022). "The connection between LMNB1 and LBR upregulation in melanoma and changes in chromatin organisation or stability described in this study were not shown before." (PMID 35883595, 2022). "Consistent with this, western blot analysis showed an increase in the cyclin-dependent kinase inhibitor p16INK4A and decreased lamin B1, Rb, and phospho-Rb in C8-infected Mel501 and SK28 melanoma cells, compared with parental and pLKO.1-infected cells." (PMID 30674989, 2019). "It became clear by our results that changes in the chromatin structure like the development of heterochromatin foci or influence on chromatin condensation are dependent on LMNB1 and the LBR in melanoma and a constant downregulation by long term treatment leads to structural and functional changes." (PMID 35883595, 2022). "Our analysis newly revealed that a downregulation of LMNB1 and the LBR might regulate mitotic processes and based on defects in replication, lead to cellular senescence and changes in chromatin state in malignant melanoma." (PMID 35883595, 2022). "Additionally, we found LMNB1 and LBR to be downregulated in the melanocytic BRAFV600E senescence model as well as in etoposide-induced senescence model in melanoma cells." (PMID 35883595, 2022). "Here, we show that over-expression of lamin B1 but not of lamin A enhanced melanoma cell migration in parallel to disruption of a perinuclear actin rim." (PMID 32987785, 2020). "Therefore, we hypothesize that a robust long-lasting LMNB1 or LBR downregulation is necessary to create a strong chromatin change and consequently a senescence phenotype in melanoma." (PMID 35883595, 2022). "Therefore, in this study, we address the functional role of LMNB1 and the LBR in melanoma." (PMID 35883595, 2022). "In this study, we revealed that LMNB1 and the LBR are higher expressed in melanoma compared to normal human epidermal melanocytes (NHEMs)." (PMID 35883595, 2022).
lung adenocarcinoma (12 papers, 2020 to 2024). A carcinoma that arises from the lung and is characterized by the presence of malignant glandular epithelial cells. "The results showed for the first time that persistent loss of LMNB1 in lung adenocarcinoma cells induced telomere shortening, DNA damage, cell cycle arrest in the G2/M phase, apoptosis, thus worsening senescence and inhibiting the proliferation of lung adenocarcinoma cells." (PMID 38824174, 2024). "Recent studies have highlighted the close correlation between lung adenocarcinoma tissue and LMNB1 expression." (PMID 38824174, 2024). "Previous studies revealed that lung adenocarcinoma cells showed LMNB1 overexpression, and the knockout of LMNB1 in these cells reduced their growth rate and colony formation ability." (PMID 38824174, 2024). "In lung adenocarcinoma, silencing of LMNB1 significantly inhibited cell proliferation capacity and cell motility." (PMID 36405011, 2022). "To further explore the effects of LMNB1 on LUAD cells, we used RNA interference in Lung adenocarcinoma cell A549 to knockdown the expression of LMNB1." (PMID 35712471, 2022). "LMNB1 is aberrantly highly expressed in lung adenocarcinoma tissues compared with tumor-adjacent tissues, thus regulating the proliferation ability of the lung adenocarcinoma cells via the AKT pathway." (PMID 36157221, 2022). "Based on the data of TCGA, we found that LMNB1 was highly expressed in not only lung adenocarcinoma, prostate cancer, cervical cancer and liver cancer, but also most other human cancer types." (PMID 35241075, 2022). "Knockdown of LMNB1 was functionally relevant for melanoma and lung adenocarcinoma (LUAD) progression by influencing cell senescence and DNA damage." (PMID 36405011, 2022). "On the contrary, the immunohistochemical analysis of lamin B1 in 86 lung adenocarcinoma samples showed a higher expression level in comparison to 14 tumor-adjacent tissue samples." (PMID 35328162, 2022). "The strongest positive correlation was found for CDK1 (RS = 0.61) and LMNB1 (RS = 0.54) in lung adenocarcinoma." (PMID 35805937, 2022). "Therefore, LMNB1 has excellent potential to function as an indicator for evaluating the clinical prognosis of patients with lung adenocarcinoma and as a target for precise treatment." (PMID 38824174, 2024). "Interestingly, the overexpression of LMNB1 in lung adenocarcinoma was identified to stimulate the proliferation of lung tumor cells through the protein kinase B (AKT) pathway." (PMID 38824174, 2024). "In addition, accumulating evidence suggests that LMNB1 is abnormally expressed in multiple malignant tumors, such as lung adenocarcinoma, gastric cancer, renal cell carcinoma and B-cell malignancies." (PMID 35436411, 2022). "Lung adenocarcinoma (LUAD) tissues highly express lamin B1 (LMNB1), compared with normal tissues." (PMID 35712471, 2022).
prostate carcinoma (11 papers, 2016 to 2025). A carcinoma that arises from epithelial cells of the prostate gland. "The less-aggressive LNCaP and moderately aggressive PC3 prostate cancer cell lines showed variable loss of lamin B1 levels in nuclear blebs resulting in a bleb-to-body ratio of ∼0.75±0.04 (mean±s.e.m.)." (PMID 39501901, 2025). "Microarray datasets from the Gene Expression Omnibus (GEO) specimens showed that the LMNB1 gene was upregulated in prostate cancer samples, in a manner associated with a higher tumor grade." (PMID 36005596, 2022). "In a tissue microarray of prostate cancer patients, decreased levels of lamin A/C and B2 were found to correlate with increased risk of lymph node metastasis and disease-specific death, while increased levels of lamin B1 were associated with disease recurrence." (PMID 39115711, 2024). "In most prostate cancer cells, lamin B1 was present in nuclear blebs at similar levels to the rest of the nucleus." (PMID 39501901, 2025). "The use of prostate cancer cell line models provides the ability to assay lamin B1 presence in a different model of human disease." (PMID 39501901, 2025). "LNCaP, an early model of prostate cancer, shows maintenance of lamin B1 and emerin similar to the most aggressive model DU145 while intermediate model PC3 shows loss of lamin B1 and emerin enrichment." (PMID 40060436, 2025). "On the other hand, lamin B1 showed reduced protein levels in the metastatic prostate cancer cell line LNCaP, compared to the control prostate cell line RWPE-1." (PMID 39115711, 2024). "Deformed nuclei and the mislocalization and low expression of lamin A/C, lamin B1, and emerin became more prominent as the invasiveness of the prostate cancer lines increased." (PMID 39115711, 2024). "Forced expression of LMNB1 in prostate cancer cells increased the mRNA level of several HRR genes, especially BRCA1." (PMID 35241075, 2022). "In vitro experiments reveal that targeting LMNB1 has a synergistic effect on prostate cancer with PARP inhibitor treatment." (PMID 35241075, 2022). "Practically, IHC staining of prostate cancer tissues in our center and qRT-PCR analysis of prostate cell lines also showed a close correlation between LMNB1 and BRCA1 expression." (PMID 35241075, 2022). "We also investigated the effects of LMNB1 knockdown on PARPi treatment response in human prostate cancer." (PMID 35241075, 2022). "Interestingly, different stages of prostate cancer do show significant changes in lamin B1 levels in nuclear blebs." (PMID 39501901, 2025). "Conversely, we would hypothesize nuclear blebs in the prostate cancer cells lines rupture infrequently, which results in their high levels of lamin B1 in the bleb." (PMID 39501901, 2025). "Furthermore, nuclear deformities including invaginations and blebs, were evident in the prostate cancer cell lines immunolabeled for lamin A/C and lamin B1, with the metastatic DU145 cells showing the highest abundance of aberrant nuclei." (PMID 39115711, 2024). "Immunofluorescence data reveal that human HT1080 fibrosarcoma and PC3 prostate cancer cell lines showed a MEF-like heterogenous decrease of lamin B1 in the nuclear bleb relative to the nuclear body while emerin levels could be enriched, similar, or depleted in the bleb." (PMID 40060436, 2025). "Immunofluorescence data revealed that human HT1080 fibrosarcoma and PC3 prostate cancer cell lines show a MEF-like heterogenous decrease of lamin B1 in the nuclear bleb relative to the nuclear body, with emerin levels that could be relatively enriched, maintained or depleted." (PMID 41047936, 2025). "Next, we compared human disease cell models of progeria and prostate cancer, which revealed yet again decreased DNA density in the nuclear bleb whereas lamin B1 was absent in progeria blebs and present in prostate cancer nuclear blebs." (PMID 39501901, 2025).
prostate carcinoma (continued). "Our studies of LNCaP cells, an early-stage prostate cancer model, reveal nuclear blebs that maintain lamin B1 and emerin levels without rupture." (PMID 40060436, 2025). "Despite lamin B1 not being silenced in prostate cancer, prostate cancer cell lines frequently have similar blebs termed lamin B-deficient microdomains (LDMDs)." (PMID 33316938, 2020).
progeria (9 papers, 2012 to 2025). "We tested nine different tail constructs: lamin B1, lamin C, mature lamin A residues 385–646 (wildtype, S612A, T643A, or S612A/T643A), and prelamin A residues 385–664 bearing the progeria-associated Δ35, Δ50, or Δ90 deletions." (PMID 29772801, 2018). "Similarly, we would hypothesize both hTRET and NGPS progeria nuclear blebs rupture frequently causing them to present low lamin B1 levels in the nuclear bleb." (PMID 39501901, 2025). "In addition to nuclear shape abnormalities and progerin expression, two additional features that have been associated with progeria are the accumulation of DNA damage inside the nucleus, as well as reduced and mislocalized expression of lamin B1, another lamin that functions together with lamin A." (PMID 30445906, 2018). "To determine quantitative levels of lamin B1 in progeria-based nuclear blebs, we used WT (hTERT) and Nestor–Guillermo progeria syndrome (NGPS) immortalized human fibroblasts to measure the relative DAPI and lamin B1 levels in bleb." (PMID 39501901, 2025). "Low levels of LMNB1 have been observed in senescent cells and fibroblasts derived from progeria patients." (PMID 30858340, 2019). "Mutations in human Lamin genes (LMNA, LMNB1, LMNB2) lead to a wide-range of diseases including muscular dystrophy, peripheral neuropathy and progeria." (PMID 31225490, 2018). "Abnormalities in lamin immunostaining and nuclear shape are reminiscent of cells with nuclear envelope abnormalities, such as from progeria models, lamin B1 mutant mice and following shRNA-mediated silencing of lamin B1." (PMID 23166514, 2012). "Live-cell imaging of lamin-B1 gene-edited cancer cells is complemented by fixed-cell imaging of rupture in: iPS-derived progeria patients cells, cells within beating chick embryo hearts, and cancer cells with multi-site rupture after migration through small pores." (PMID 35293271, 2022).
ataxia telangiectasia (8 papers, 2013 to 2025). Ataxia-telangiectasia is the association of severe combined immunodeficiency (affecting mainly the humoral immune response) with progressive cerebellar ataxia. "Mutations in LMNB1, which encodes lamin B1, lead to a broad range of diseases including autosomal dominant leukodystrophy, ataxia–telangiectasia, and neural tube defects." (PMID 37108075, 2023). "In contrast, Autosomal Dominant Leukodystrophy (ADLD) and ataxia telangiectasia (AT) are linked with increased lamin B1 expression." (PMID 32183360, 2020). "High level of Lamin B1 in Ataxia telangiectasia cells results in altered nuclei and senescence, which is parallel to what we have demonstrated in OCI-MY5 and RPMI-8226 cells." (PMID 38804044, 2024). "An increase in Lamin B1 levels has also been reported in Ataxia telangiectasia (AT) and Werner syndrome (WRN) cells." (PMID 33918867, 2021). "Previous studies have reported that p38 MAPK (mitogen-activated protein kinase) is activated by ROS in ataxia-telangiectasia cells and that the level of endogenous Lamin B1 is increased in these cells, resulting in nuclear deformation and senescence." (PMID 31164634, 2019). "Increased levels of lamin B1 have also been observed in lymphoblasts and fibroblasts from patients who suffer from ataxia telangiectasia (AT)." (PMID 28854936, 2017). "In Ataxia telangiectasia patients and in chronic kidney disease, an ATM-independent lamin B1 upregulation in response to oxidative stress was found." (PMID 39979866, 2025). "As AT is caused by a mutation in the protein kinase ataxia telangiectasia mutated (ATM) that controls DNA damage response signaling, the link between AT and elevated levels of lamin B1 remains unsolved." (PMID 28854936, 2017).
colorectal cancer (8 papers, 2016 to 2025). A primary or metastatic malignant neoplasm that affects the colon or rectum. "Increasing lamin B1 expression can cause the senescence of colorectal cancer cells." (PMID 27449096, 2016). "To achieve this in B-type lamins, we CRISPR-engineered HCT116 colorectal carcinoma epithelial cells and knocked in the mini auxin-inducible degron and mClover at the end of endogenous lamin B1 (LMNB1) and lamin B2 (LMNB2) gene loci." (PMID 38519987, 2024). "It is possible that these molecules LMNB1 and JUN act alone as markers of early colorectal cancer metastasis, or in combination with each other, but this requires validation by clinicians in clinical therapies." (PMID 39390002, 2024). "We suggest that the differentially expressed genes LMNB1 and JUN are potential targets for predicting colorectal cancer metastasis." (PMID 39390002, 2024). "LMNB1 and JUN are potential target genes for predicting colorectal cancer metastasis." (PMID 39390002, 2024).